IL10 (interleukin 10)
Diseases named in the same sentence as IL10 in open-access papers (continued):
Sharing a sentence is not in itself a finding about the gene and the disease.
fungal infections (continued). "Further, a significant variation in IL-17A, TNF-β, IL-1β, IL-2, IL-4, IL-6, IL-8, IL-10, IL-22, and IL-12p70, between the uninfected group and the pulmonary bacterial and fungal infection group (P < 0.05) was observed." (PMID 36319826, 2022). "HIF-1α inhibition increased TNF and IL-10 levels after Candida infection, and it has been previously shown that HIF-1α controls progression of fungal infections by limiting IL-10 production." (PMID 32999407, 2020). "During fungal infection, IL-12 and IL-10 act as regulators of Th cell growth and humoral immune responses." (PMID 32801570, 2020). "During fungal infections PMNs rely on the NFATc pathway to efficiently kill pathogens and resolve inflammation through IL-10 production." (PMID 31921172, 2019). "Regarding fungal infection, IL-10 has been reported to inhibit the defense against C. albicans infection by reducing the activation of IFN-γ producing Thl cells and macrophages, leading to impaired fungal clearance." (PMID 31474988, 2019). "Other cytokines also related to fungal infections are IL-8, IL-10, and IL-15, as well as the already mentioned IL-17." (PMID 31484389, 2019). "Our understanding IL-10 in the context of fungal infections is less developed although investigations involving the endemic fungal pathogen C. neoformans have proven particularly informative." (PMID 27973396, 2016). "An overabundance of IL-10 impairs fungal clearance and appears essential for the development of persistent fungal infections." (PMID 27973396, 2016). "A number of clinical observations suggest an inverse relationship between IFN-γ and IL-10 production in patients with fungal infections." (PMID 25360137, 2014). "This was in association with a decreased recovery of granulocytes compared to primary infection, consistent with published data on Gr-1+ cells in IL-10−/− mice after bleomycin-induced lung injury or fungal infection." (PMID 21647373, 2011). "It is also worth mentioning that levels of the anti-inflammatory cytokine IL-10 were also reduced significantly, which indicates a complex interaction of cytokines and chemokines in response to fungal infections." (PMID 18282300, 2008). "Based on their cytokine secretion and functions during fungal infections, T cells are classified into Th1 (IFNγ, GM-CSF, and TNFα), Th17 (IL-17A/F), Th22 (IL-22), Th2 (IL-4 and IL-13), Th9 (IL-9 and IL-10), Treg (IL-10 and TGFβ), and Tr1 (IL-10)." (PMID 36177012, 2022). "Overall the cytokine pattern observed in this study using long-term dexamethasone treatment and concomitant fungal infection, namely lowering of IL-1β, IL-6, and IL–8 and an increase in IL-10, implicates a shift from Th1 towards Th2, a pattern associated with suppressing antifungal properties." (PMID 33803702, 2021). "Moreover, ethanol consumption was able to down modulate IL-1β and IL-10 levels after fungal infection." (PMID 32701055, 2020). "IL-10 is known to have a strong inhibitory effect on fungal infection." (PMID 32801570, 2020). "Accordingly, an inverse relationship between IL-10 and IFN-γ was suggested by several investigators that may potentially result in a high susceptibility to fungal infections especially in those patients presenting with high IL-10 levels." (PMID 28820494, 2017). "Interestingly, the most significant IL-10 increase in peripheral blood was observed for the group of neonatal sepsis subjects with fungal infection, thereby confirming previous findings that fungal infection is commonly associated with immune suppression." (PMID 28367457, 2017). "Although multiple immune processes contribute to immune regulation in response to fungal infections, we focused our attention on the IL-10, PD-1, and CTLA-4 signaling pathways as individually and collectively they have proven to be of central importance to numerous immunoregulatory networks." (PMID 27973396, 2016).
fungal infections (continued). "Thus, studies to date identify the IL-10 signaling pathway as a critical contributor to the immunoregulatory networks that develop in response to fungal infections." (PMID 27973396, 2016). "However, the delicate balance of IL10/IFNγ needs to be in check since high level of IL10 suppresses the activity of IFNγ which provides the main Th1 defense against fungal infections." (PMID 26635780, 2015). "Recent evidences linking impairment in the IL-12/interferon (IFN)-γ axis to susceptibility to disseminated PCM, and the high levels of IL-10 detected in the severe forms of various mycosis, strongly indicate that IL-10 exerts deleterious effects on fungal infections." (PMID 24205424, 2013). "According to the relatively high IL-10 level after S. schenckii infection, we speculate the alternatively activated macrophages (M2 cells) and the primary IL-10-producing innate cells are involved in anti-fungal infection." (PMID 23285072, 2012). "Likewise, IL-10 blockade increased clearance and abrogated hematogenous dissemination of C. neoformans to the brain implying this strategy has therapeutic potential in treatment of fungal infections." (PMID 38846955, 2024). "Thus IL-10 could be considered a signature of mould infection and could be exploited as a novel supportive biomarker in the diagnosis of invasive mycosis." (PMID 38980880, 2024). "IL-10 acts primarily with immunosuppressive functions on leukocytes, whereas other members of the family act preferentially on epithelial cells, where they control defense mechanisms against viral, bacterial, and fungal infections, protect tissue integrity, and promote repair and regeneration." (PMID 36357780, 2022). "The balance between the anti-inflammatory IL-10 and pro-inflammatory cytokines, such as IL-12, seems to be a key factor for an adequate inflammation in fungal infection, since IL-10 might be required for limiting high levels of inflammation and the consequent host damage." (PMID 30500849, 2018). "IL-10 represents an important cytokine that may affect the Th1/Th2 balance in fungal infections." (PMID 28542438, 2017). "Interestingly, dectin-1 also induces the production of IL-10, an anti-inflammatory cytokine whose role during fungal infection which leads to the activation of leukocytes may be important for limiting host injury during severe inflammation." (PMID 28248219, 2016). "We also investigated the influence of PD-L1, IL-10, and nitrotyrosine in the suppressive activity of lung-infiltrating MDSCs of C57BL/6-WT, Dectin-1KO, TLR2KO, and TLR4KO mice after in vivo fungal infection." (PMID 39035356, 2024). "There were significant differences in IL-4, IL-6, IL-8, IL-10, IL-12p70, IL-1β, IL-2, TNF-β, IL-17, and IL-22 between the uninfected group and the pulmonary bacterial and fungal infection group (P < 0.05)." (PMID 36319826, 2022). "The most discriminatory parameters for secondary bacterial/fungal infections (p-value, ROC-AUC, 95% CI) were CRP (p = 0.0005, 0.77, 0.65–0.88), IL-10 (p < 0.0001, 0.88, 0.73–0.94), and PCT (p = 0.0008, 0.76, 0.65–0.88)." (PMID 36275812, 2022). "There were significant differences in IL-6, IL-8, IL-10, IL-12p70, and TNF-β between the pulmonary bacterial infection group and the pulmonary bacterial, fungal infection group (P < 0.05)." (PMID 36319826, 2022). "Meanwhile, anti-inflammatory cytokine IL-10 and type 2 cytokines (IL-4, IL-5, and IL-13) were similar in the WT or CD146 KO mice with fungal infection." (PMID 33537006, 2020). "Thus, a high level of IL-10 in a host’s serum may inhibit the development of fungal infections." (PMID 32801570, 2020). "High levels of IL-10 that downregulate IFN-γ production are detected in chronic candidiasis, in the severe forms of endemic mycoses and in neutropenic patients with aspergillosis, and thus have been linked to susceptibility to fungal infections." (PMID 28542438, 2017).
fungal infections (continued). "High levels of IL-10, negatively affecting IFN-γ production, are detected in chronic candidal diseases, in the severe form of endemic mycoses, and in neutropenic patients with aspergillosis." (PMID 25360137, 2014). "In the single fungal infection group, cytokines IFN-γ, IL-10 and IL-17 kept increasing in the first few weeks of infection to a peak which was followed by gradual decrease." (PMID 23285072, 2012). "Compared to TNF-α and IL-10, CCL3/MIP-1⍺ plays an important role in recruiting various cells such as monocytes, macrophages, lymphocytes, and eosinophils via the CCR1 or CCR5 receptor, thereby strengthening the immune response against a fungal infection." (PMID 38967888, 2024). "Our study also found that after fungal infection, Dectin-1 affected the expression levels of phenotype-related factors (TNF-α, INOS, IL-6, IL-12, Arg-1, or IL-10) in M1 and M2-type macrophages through the regulation of MAPK signaling pathways, such as p38, JNK, and ERK." (PMID 39478855, 2024). "Chitin induces interleukin 10 (IL-10) production in neutrophils and macrophages through a nucleotide-binding oligomerization domain with protein 2 (NOD2)-dependent pathway to inhibit host pro-inflammatory response during fungal infection." (PMID 34234752, 2021). "While there is limited knowledge on the modulation of anti-inflammatory processes by microglia in the setting of fungal infections, a previous study had shown that, an infection with C. albicans (in mice) induces immunosuppression by activating TLR-2, leading to the release of IL-10." (PMID 32899547, 2020). "IL-10 signaling: IL-10 is an anti-inflammatory cytokine expressed by Tregs and DCs that prevents excessive inflammation by limiting the production of IL-1, IL-6, IL-23, IFN-γ, and TNF-α during fungal infections." (PMID 30761136, 2019). "This predicts that, in the case of chronic fungal infections dominated by non-resolving, persisting inflammation, IL-10 produced by Treg cells acts as homeostatic host-driven response to keep inflammation under control." (PMID 25360137, 2014). "In summary we report here that MSKs play important roles in regulating IL-10 production downstream of fungal PAMPS, suggesting that MSKs could play a role in the control of fungal infection." (PMID 23533666, 2013). "Despite the great number of evidences demonstrating the suppressive role of IL-10 and its detrimental effects to human and experimental fungal infections, direct studies investigating the consequences of IL-10 ablation in the immunity to PCM have not been performed so far." (PMID 24205424, 2013). "Because the LPS stimulus (TLR4 agonist) induces IL-10 production that is not controlled by galectin-3, we suppose that our observations may be peculiar to fungal infections." (PMID 19229338, 2009). "IL-10 alone could rule out secondary bacterial/fungal infections with an negative predictive value (NPV) of 89% (cut-off: 15.4 ng/mL), providing intensivists with a much needed tool to avoid unnecessary antibiotic therapy and to treat actual secondary infections as soon as possible." (PMID 36275812, 2022). "The levels of IL-6, IL-8, and IL-10 in CML patients with bacterial and fungal infections of the lung were significantly higher than those without infection." (PMID 37114211, 2023). "However, within the presented investigation of our workgroup, high IL-10 levels could be observed in patients suffering from a fungal colonization or infection in parallel with elevated IFN-γ levels, thus being a consequence, rather than a cause of the underlying fungal infection." (PMID 28820494, 2017).
ischemia (63 papers, 2008 to 2025). A hypoperfusion of the BLOOD through an organ or tissue caused by a PATHOLOGIC CONSTRICTION or obstruction of its BLOOD VESSELS, or an absence of BLOOD CIRCULATION. "In an intraocular neovascularization model focusing on IL-10’s role in macrophage polarization, IL-10 was implicated as being indirectly angiogenic since ischemia-induced pathological angiogenesis in the retina was promoted in the presence of IL-10." (PMID 35159396, 2022). "A treatment with interleukin-10-loaded (IL-10+) EVs significantly ameliorated renal tubular injuries and inflammation caused by an ischemia/reperfusion injury, and powerfully prevented the transition to chronic kidney disease." (PMID 36555585, 2022). "The M2 phenotype has beneficial effects, it causes ischemic brain healing post-ischemia and the release of anti-inflammatory factors, such as IL-4 and IL-10, and secretes many factors with neurotrophic properties capable of preventing the development of neuroinflammation." (PMID 33922467, 2021). "Exosomes derived from MSCs can ameliorate inflammation after acute ischemia or ischemia–reperfusion injury by modulating anti-inflammatory molecules (IL-4 and IL-10) and pro-inflammatory cytokines (IL-6, TNF-α, and IL-1β), and inhibiting microglia activation." (PMID 40771978, 2025). "IL-10, an anti-inflammatory cytokine, was reduced in ischemia, leading to brain damage and neuronal death." (PMID 39877642, 2025). "IL10 was found to decrease renal damage in different models of renal damage, including transplantation of a marginal kidney, ischemia, and CP-mediated kidney injury in murine animals." (PMID 38731418, 2024). "Treg cells can also secrete a potent anti-inflammatory cytokine: IL-10, mediating Treg-induced blood flow restoration and neovascularization improvement after ischemia." (PMID 37794487, 2023). "Recently, compelling evidence has delineated the role of DCs in hepatic I/R injury and several results support that DCs modulate levels of IL-6 and IL-10 in liver submitted to ischemia injury." (PMID 37593740, 2023). "IL-10 gene transfer with an adenovirus vector reduced infarct volume in a rat model of photothrombotic ischemia." (PMID 37196130, 2023). "Overall, we discovered that G-CSF can improve EPC angiogenic function through a hypoxia/IL-10 signaling cascade and impede neovascular growth in response to ischemia of SNx mice." (PMID 37896140, 2023). "During an ischemia-reperfusion injury, T-regulatory cells exhibit a protective role in ischemia and reperfusion by secreting IL-10 to reduce the ischemia-reperfusion injury." (PMID 36555585, 2022). "Nevertheless, systemic intravenous hiPSC-MSC infusion in the MSC-MSC/once, MSC-MSC/week and MSC-MSC/3 days groups significantly improved IL-10 compared with the ischemia group (all p < 0.05)." (PMID 36008710, 2022). "Many cytokines and chemokines such as IL-10 also affect hindlimb ischemia-induced inflammation and angiogenesis." (PMID 33815358, 2021). "Macroscopic observations associated with an acute ischemia of the affected hind-limb, termed critical ischemic events (CIE), were recorded after FAL and treatment with IL10 and anti-IL10." (PMID 32316628, 2020). "IL-10 treatment significantly improved cell viability (P < 0.05 vs. H2O2 + Hb under ischemia), indicating direct cardioprotection of IL-10 against ischemic injury in cardiomyocytes." (PMID 32879134, 2020). "The same effect on the IL-10 level has been demonstrated after intranasal BDNF administration after ischemia." (PMID 32219700, 2020). "BDNF can suppress TNF-α and its mRNA expression, this exacerbating ischemia-induced injury, while it increases IL-10 and its mRNA expression, which play an anti-inflammatory neuroprotective role." (PMID 30622436, 2018). "Exogenous administration of the anti-inflammatory cytokine, interleukin 10 (IL-10), is known to promote neuroprotection and mitigate neuroinflammation after ischemia." (PMID 24499655, 2013).
ischemia (continued). "At P12, HI and LPS+HI increased IL-10 expression in both hemispheric gray and white matters ipsilateral to ischemia." (PMID 21599903, 2011). "TNF-α, as an important proinflammatory cytokine, appears to exacerbate cerebral injury of ischemia while IL-10, an anti-inflammatory cytokine, ameliorates ischemic insult of brain." (PMID 21490702, 2010). "Our data, however, would suggest that BCAS 14d and 28d mouse brains showed evidence of an anti-inflammatory or neuroprotective state as shown by a significant increase in the expression of S100A10, IL-10, Nrf2, and TRPA1, all of which have been linked to ischemia-induced neuroprotection." (PMID 40895091, 2024). "Interestingly, CDNF was shown to possess anti-inflammatory capacity by inducing the production of IL-10 that plays pivotal roles in neuroprotection after ischemia." (PMID 36792604, 2023). "Resolvin D1 (100 μg/kg, intravenous) did not inhibit an increase in IL-10 post lung I/R injury, and MaR1 (4 ng/g body weight) administered prior to ischemia in a rat model of liver I/R injury increased serum IL-10 levels that were otherwise reduced post-I/R injury." (PMID 35391753, 2022). "Notably, macrophages showed significantly increased IL-10 level on days 7 and 14, whereas microglia showed a significant upregulation only on day 14, suggesting that the IL-10 production of macrophages and microglia is delayed following ischemia." (PMID 34772416, 2021). "Furthermore, symptoms of ischemia on ligated hind-limbs had the highest incidence after application of anti-IL10." (PMID 32316628, 2020). "Available evidence reveals that IL-10 can induce NF-κB activation in neurons and hypoxia-ischemia can induce two peaks of NF-κB activity in the brain: an early NF-κB activation contributing to neuronal damage and a late activation resulting in protection for neurons." (PMID 31801113, 2019). "Moreover, there is evidence that IL10 can be elevated very early in models of ischemia and intracerebral hemorrhage and that microglia can initially undergo alternative activation and then progress to classical activation in vivo." (PMID 25148577, 2014). "Moreover, post-ischemic IL-10 gene transfer attenuated brain infarction in rats subjected to focal and global ischemia." (PMID 24499655, 2013). "Anti-inflammatory cytokines such as TGFβ1 and IL-10 have a beneficial function after ischemia." (PMID 22028848, 2011). "Our data suggested that BDNF might protect brain from ischemia through upregulating local IL10 in brain." (PMID 21490702, 2010). "The upregulation of let-7a-5p in microglia has been found to correlate with protection from ischemia and neuroinflammation by inhibiting the expression of pro-inflammatory factors (e.g., IL-6, iNOS) and boosting the expression of anti-inflammatory factors (IL-10 and IL-4)." (PMID 35682695, 2022). "Nonetheless, repeated systemic intravenous hiPSC-MSC infusion in the MSC-MSC/week and MSC-MSC/3 days groups significantly increased IL-10 and VEGF compared with the ischemia group (all p < 0.05)." (PMID 36008710, 2022). "While percentage of IL10+ macrophages was unchanged, but percentages of TNF-α+ and IFN-γ+ macrophages were increased in PD-1-/- mice after hindlimb ischemia." (PMID 33815358, 2021). "To evaluate the effect of RAC transplantation on severe ischemia tissues in MCAO, we examined the expression profiles of anti-inflammatory cytokine, IL-10, and angiogenesis factor, VEGF, at the early phase of recovery (day 7) in the peri-infarct area." (PMID 30682162, 2019). "Our results suggest that PDGF-EVs are enriched in anti-inflammatory and immunomodulatory factors and induced in PBMC an enhanced production of IL-10 and TGF-β1 resulting in protection of muscle from acute ischemia in vivo." (PMID 30514962, 2018). "We detected the expression of mRNAs for various inflammatory cytokines (IL-1β, TNF-α, IL-6, IL-10, and TGF-β) in the cortex ipsilateral to sites of ischemia 24, 48, and 72 h after reperfusion." (PMID 27549161, 2016).